HOXC6 (homeobox C6)
Diseases named in the same sentence as HOXC6 in open-access papers (continued):
Sharing a sentence is not in itself a finding about the gene and the disease.
oral cancer (5 papers, 2020 to 2025). "HOXC6 is closely associated with poor survival of patients with oral cancer." (PMID 35008435, 2021). "In this study, we investigated the miRNA profile of HOXC6-induced oral cancer cells using miRNA expression chip technology, and our main goal was to identify differentially expressed miRNAs to study novel mechanisms underlying the effects of HOXC6." (PMID 35008435, 2021). "In our previous studies, HOXC6 performs a key function in oral squamous cell carcinoma and is abnormally expressed in oral cancers." (PMID 35008435, 2021). "Furthermore, siRNA against HOXC6 significantly reduces the growth of xenograft tumors in mice with oral cancer and upregulation of miR-495 can inhibit the growth of OSCC xenografts in vivo, which were in agreement with our in vivo experimental results." (PMID 32171324, 2020). "HOXC6 was found to be abundantly expressed in oral cancer FaDu-PTX cells compared to normal cells." (PMID 32171324, 2020). "In contrast, HOXA7, HOXA10, HOXB7, HOXC6, HOXC10, HOXD10, and HOXD11 were consistently upregulated in potentially malignant oral lesions as they advanced to oral cancer." (PMID 41477365, 2025). "HOXA7, HOXA10, HOXB7, HOXC6, HOXC10, HOXD10, HOXD11 showed consistent upregulation in the potentially malignant oral lesions through their progression to oral cancer, which indicated the posterior prevalence of the HOX genes during cancer progression." (PMID 35710803, 2022). "However, studies on the miRNA and HOXC6 networks in oral cancer cells have not been reported." (PMID 35008435, 2021).
oral squamous cell carcinoma (5 papers, 2020 to 2025). "It has also been reported that oral squamous cell carcinoma (OSCC) patients have a high expression of HOXC6, suggesting a role of aberrant HOX gene expression in the development of OSCC." (PMID 35008435, 2021). "The purpose of this study is to determine the roles of genes DKK1, HOXC6, and YKT6 in biopsy-proven oral squamous cell carcinomas and to correlate tumour severity with gene expression levels." (PMID 41477365, 2025).
esophageal squamous cell carcinoma (4 papers, 2019 to 2023). Esophageal squamous cell carcinoma (ESCC) is a type of esophageal carcinoma (EC) that can affect any part of the esophagus, but is usually located in the upper or middle third. "Homeobox C6 (HOXC6) can be used as a prognostic marker in patients with esophageal squamous cell carcinoma since the median survival time of patients with high HOXC6 expression is found to be poor." (PMID 32171324, 2020). "However, the role of HOXC6 in esophageal squamous cell carcinoma (ESCC) remains largely uninvestigated." (PMID 30886783, 2019).
lung adenocarcinoma (4 papers, 2017 to 2025). A carcinoma that arises from the lung and is characterized by the presence of malignant glandular epithelial cells. "Gene knockdowns were used to verify the effects of HOXB7 and HOXC6 on the proliferation and migration of lung adenocarcinoma (LUAD) cells." (PMID 39980564, 2025). "We further verified their role in the development of lung adenocarcinoma by knocking down HOXB7 and HOXC6 in A549 and NCI-H1975 cells respectively." (PMID 39980564, 2025). "In lung adenocarcinoma cell lines, HOXB7 and HOXC6 were confirmed to markedly influence cell proliferation and migration, suggesting consideration as prognostic indicators." (PMID 39980564, 2025).
osteosarcoma (4 papers, 2016 to 2025). A usually aggressive malignant bone-forming mesenchymal neoplasm, predominantly affecting adolescents and young adults. "In osteosarcomas, the TGF-β superfamily seems to regulate the expression of HOXC6." (PMID 30559605, 2018).
breast tumors (3 papers, 2011 to 2020). "Similarly, in MCF-7 cells and in mammary glands of S–D rats, expression of HOXC6, commonly upregulated in breast tumor tissue, increases upon BPA incubation by enhancing H3K4me3, histone acetylation and recruitment of RNA polymerase II." (PMID 32796699, 2020).
lymph node metastasis (3 papers, 2020 to 2025). "High expression levels of HOXC6 have also been found to be associated with lymph node metastasis." (PMID 33076847, 2020). "There were 7.45-fold and 16.98-fold increases in the HOXC6 mRNA level in the AGC tissues without lymph node metastasis and with lymph node metastasis, respectively, compared to that observed in the matched normal gastric tissue." (PMID 32745141, 2020).
medulloblastoma (3 papers, 2016 to 2023). A malignant, invasive embryonal neoplasm arising from the cerebellum. "Based on the single-cell data of 13 medulloblastomas, we observed that three HOXC genes (HOXC4, HOXC5, and HOXC6) were expressed in neurons and neuroepithelial cells, specifically within the WNT and Group 3 subtypes of medulloblastoma." (PMID 37547473, 2023).
nasopharyngeal carcinoma (3 papers, 2018 to 2020). A carcinoma arising from the nasopharyngeal epithelium. "In nasopharyngeal carcinoma, HOXC6 is an independent prognostic parameter for NPC patients, and HOXC6 expression is positively correlated with the Ki-67 proliferation index." (PMID 32509568, 2020). "It has been reported that there are correlations of HOXC6 overexpression with increment of tumor stage, advanced nodal status in nasopharyngeal carcinoma." (PMID 30559605, 2018).
neuroblastoma (3 papers, 2018 to 2019). Neuroblastoma (NB) is the most common solid, extracranial childhood tumor. "In neuroblastoma, however, the HOX genes have been linked to differentiating cells and specifically HOXD1 identified here (as well as HOXC6 and HOXD8) are associated with differentiation towards a neuronal phenotype." (PMID 29757368, 2018). "HOXC6 and HOXC11 have been shown to induce differentiation of GOTO neuroblastoma cells into Schwannian cells via transcription activation of S100β." (PMID 31379707, 2019).
acute myeloid leukaemia (2 papers, 2017 to 2019). "Overexpression of the HOXC6 gene induces gene expression programs similar to acute myeloid leukemia." (PMID 31681584, 2019).
esophageal cancer (2 papers, 2020 to 2025). A primary or metastatic malignant neoplasm involving the esophagus. "Furthermore, HOXC6 expression was elevated in multiple tumor types, including stomach adenocarcinoma, invasive breast carcinoma, and esophageal carcinoma, highlighting its critical role in various cancers." (PMID 40255403, 2025).
head and neck cancer (2 papers, 2020 to 2021). A primary or metastatic malignant neoplasm affecting the head and neck. "In all types of head and neck cancer (n = 500), high HOXC6 expression was significantly associated with low survival (log-rank p = 0.0005)." (PMID 35008435, 2021).
Obesity (2 papers, 2019 to 2025). Accumulation of substantial excess body fat. "Methylation of several gene promoters, such as HAND2, HOXC6, and PPARG, influences adipogenesis and differentiation, obesity, lipid metabolism, and adipose tissue expandability." (PMID 30911298, 2019).
ovarian carcinoma (2 papers, 2016 to 2022). A malignant neoplasm originating from the surface ovarian epithelium. "In addition, the expression of HOXC6 in ovarian cancer and melanoma was low." (PMID 35488304, 2022).
rectal cancer (2 papers, 2023 to 2024). A primary or metastatic malignant neoplasm that affects the rectum. "In summary, we identified five radiosensitivity-related genes associated with rectal cancer prognosis: TOP2A, MATR3, APOL6, JOSD1, HOXC6." (PMID 38012642, 2023). "In subsequent studies, we will perform cell function experiments, xenograft experiments in nude mice, and molecular mechanism experiments on irradiated human rectal cancer cell lines after overexpression or knockdown of TOP2A, MATR3, APOL6, JOSD1, and HOXC6." (PMID 38012642, 2023). "Through the random survival forest analysis of these 1153 differential genes, we finally screened five key genes, which were the radiosensitivity up-regulated genes of rectal cancer: TOP2A, MATR3, APOL6, JOSD1 and the radiosensitivity down regulated gene of rectal cancer: HOXC6." (PMID 38012642, 2023). "qRT-PCR revealed that MATR3 expression was different in rectal cancer tissues and adjacent non-cancerous tissues, while APOL6, HOXC6, JOSD1, and TOP2A expression was not different." (PMID 38012642, 2023).
Type 2 diabetes (2 papers, 2015 to 2022). "In addition, genes that are important for muscle functions such as (MAPK1), Myosin XVIIIB (MYO18B), Homeobox C6 (HOXC6), and AMP-activated protein kinase subunit (PRK AB1) were compared between individuals with or without a family history of Type 2 diabetes." (PMID 36295527, 2022).
bladder cancer (1 paper, 2023). "The expression of HOXC4, HOXC5, HOXC6, and HOXC11 was detected in 60%, 86%, 100%, and 80% of bladder cancer tissues, respectively." (PMID 37627900, 2023). "Four genes (HOXC4, HOXC5, HOXC6, and HOXC11) located at the HOX C locus as well as one gene (HOXD11) located at the HOX D locus were not expressed in normal bladder tissues but expressed in most bladder cancer tissues." (PMID 37627900, 2023).
carcinoid (1 paper, 2016). "HOXC6 expression in cultured human BON1 carcinoid cells enhanced cell proliferation and activated the oncogenic activator protein-1 signaling pathway through JunD." (PMID 27081081, 2016).
carotid atherosclerosis (1 paper, 2021). A thickening and loss of elasticity of the walls of carotid arteries that occur with formation of atherosclerotic plaques. "HOXC cluster antisense RNA 1 (HOXC‐AS1) and homeobox C6 (HOXC6) were shown to be downregulated in carotid atherosclerosis via microarray analysis." (PMID 33340430, 2021).
cervical adenocarcinoma (1 paper, 2025). An adenocarcinoma arising from the cervical epithelium. "We hypothesize that, even with the small number of samples used (randomized selection), there is strong evidence that the selected genes, HOXC6, HOXC8, RARβ, BCL2, and E6/E7, can be used as a pan early cervical adenocarcinoma test." (PMID 40361484, 2025).
cognitive decline (1 paper, 2024). "HOXC5- and HOXC6-associated DMP cg08254359 was significantly correlated with the cognitive decline speed, namely, mPACCdigit_speed (r = −0.12, p = 2.76E-02) and mPACCtrailsB_speed (r = −0.12, p = 2.92E-02)." (PMID 38298218, 2024).
dilated cardiomyopathy (1 paper, 2023). Cardiomyopathy which is characterized by dilation and contractile dysfunction of the left and right ventricles. "Related signaling pathway enrichment analysis revealed that the pathways enriched by GO of HOXC6 gene were exploration behavior, muscle fiber development and ecm receptor interaction, dilated cardiomyopathy and other pathways." (PMID 38012642, 2023).
influenza (1 paper, 2022). An acute viral infection of the respiratory tract, occurring in isolated cases, in epidemics, or in pandemics; it is caused by serologically different strains of viruses (influenzaviruses) designated A, B, and C, has a 3-day incubation period, and usually lasts for 3 to 10 days. "Because the encoded HoxC8 and HoxC6 proteins promote IAV replication, active loop formation at the HoxC8-HoxC6 loci, as a consequence of NP-dependent disruption of the Suv4-20h2-cohesin interaction, contributes to influenza-induced pathology (right)." (PMID 36398441, 2022).
keloid (1 paper, 2022). An irregularly shaped, elevated mark on the skin caused by deposits of excessive amounts of collagen during wound healing. "In this study, we first identified a crucial role for HOXC6 in the pathogenic mechanism of KFs in keloids and documented that HIF-1α positively regulates HOXC6 expression in KFs, thereby contributing to the progression of keloids." (PMID 35547861, 2022). "Further experiments are needed to specify the molecular mechanisms underlying the interaction between HIF-1α and HOXC6, which might provide great insights into the pathogenic mechanism of hypoxia in keloids." (PMID 35547861, 2022). "HOXC6 was the top-ranking hub gene of KFs in microarray datasets from GEO and was upregulated in keloid tissue samples and KFs." (PMID 35547861, 2022). "Homeobox C6 (HOXC6) emerged as a hub gene in KFs from the GEO database was verified in keloid tissue samples and KFs using reverse transcription-quantitative polymerase chain reaction, western blot (WB) and immunohistochemistry." (PMID 35547861, 2022). "Based on our results, HOXC6 was overexpressed in keloid tissue samples and KFs, which subsequently promoted KF proliferation and migration and inhibited KF apoptosis." (PMID 35547861, 2022). "In conclusion, our study first showed that HOXC6 functions as an oncogenic driver in keloids by promoting KF proliferation, migration and ECM synthesis while inhibiting KF apoptosis." (PMID 35547861, 2022). "Overall, our results indicate the importance of the HIF-1α/HOXC6/ERK pathway in keloid growth and invasion, and further molecular mechanistic research and in vivo experiments are warranted to validate the clinical utility of these findings." (PMID 35547861, 2022). "Our findings first revealed that HOXC6 acts as an oncogenic driver in the molecular mechanisms of fibroblasts in keloids." (PMID 35547861, 2022). "Among these genes, HOXC6 had the highest degree in the PPI network and was therefore selected as a candidate gene associated with keloid pathogenesis for further confirmation." (PMID 35547861, 2022). "Consistently, elevated mRNA and protein expression levels of HOXC6 were observed in keloid tissue samples and KFs." (PMID 35547861, 2022). "Consistent with predictions, the HOXC6 mRNA level was significantly higher in keloid tissues than in normal skin tissues." (PMID 35547861, 2022). "We conducted transcriptome sequencing analyses and in vitro experiments to explore the pathways downstream of HOXC6 in keloids." (PMID 35547861, 2022). "RT-qPCR, WB and immunohistochemistry analyses were performed to confirm the expression of HOXC6 in keloids." (PMID 35547861, 2022). "Taken together, HOXC6 may serve as a promising novel therapeutic target and new focus for research designed to understand the pathogenesis of keloids." (PMID 35547861, 2022). "Taken together, HOXC6 may represent a promising novel therapeutic target and a new focus for research designed to understand keloid pathogenesis." (PMID 35547861, 2022). "This study is the first to explore the role of HOXC6 in keloid pathology and development." (PMID 35547861, 2022). "Based on the information provided above, we hypothesized that HOXC6 may play a key role in keloid progression." (PMID 35547861, 2022). "The HIF-1α/HOXC6/ERK axis promotes proliferation, migration and ECM production by KFs, contributing to the progression of keloids." (PMID 35547861, 2022). "However, the role of HOXC6 and its specific mechanism in keloids remain unclear." (PMID 35547861, 2022). "Since HIF-1α is a core factor that mediates hypoxic stress and plays a key role in keloid development, the JASPAR database was used to forecast the possible HIF-1α binding sites within the HOXC6 promoter region." (PMID 35547861, 2022). "We explored the effects of HOXC6 downregulation on cell proliferation, migration, apoptosis and ECM synthesis to determine the function of high HOXC6 expression in keloids and KFs." (PMID 35547861, 2022).
keloid (continued). "Furthermore, we first explored the function of the HIF-1α/HOXC6 axis via the ERK/MAPK pathway in KFs, providing candidate novel therapeutic targets for keloids." (PMID 35547861, 2022). "Given the lack of previous reports of the role of HOXC6 in keloid, we further validated the significance of high HOXC6 expression in keloid tissue samples and KFs and explored the potential pathogenic mechanism of HIF-1α-induced HOXC6 expression in KFs." (PMID 35547861, 2022).
liver cancer (1 paper, 2018). An epithelial or non-epithelial malignant neoplasm that arises from the liver. "HOXC6 overexpression correlated with high AFP level (P = 0.038), liver cirrhosis (P = 0.044), larger tumor (P = 0.001), vascular invasion (P = 0.046) and Barcelona Clinic Liver Cancer (BCLC) stage (P = 0.005)." (PMID 29348394, 2018).
liver cirrhosis (1 paper, 2018). "In addition, HOXC6 overexpression was positively associated with high AFP level, liver cirrhosis, larger tumor, vascular invasion and BCLC stage." (PMID 29348394, 2018). "Kaplan-Meier analysis showed that the patients with high expression of HOXC6, high AFP level, high gamma-glutamyltransferase (GGT) level, liver cirrhosis, larger tumor or vascular invasion had poorer OS time (all P < 0.05)." (PMID 29348394, 2018). "HOXC6 expression was positively correlated with high AFP level, liver cirrhosis, larger tumor, vascular invasion and BCLC stage." (PMID 29348394, 2018). "Furthermore, high HOXC6 expression, high AFP level, high GGT level, liver cirrhosis, larger tumor, tumor number, satellite nodule and vascular invasion were unfavorable predictors for TTR of HCC patients (all P < 0.05)." (PMID 29348394, 2018).
metastatic cancers (1 paper, 2021). A carcinoma which has spread from the original site of growth to another anatomic site. "Our novel observation of increased HOXC6/miR-188-5p expression and its oncogenic activity in cancer cells suggests that HOXC6/miR-188-5p may serve as a diagnostic and, ultimately, a therapeutic tool for the effective clinical management of metastatic cancers." (PMID 35008435, 2021).
metastatic prostate carcinoma (1 paper, 2017). A carcinoma that arises from the prostate gland and has spread to other anatomic sites. "The central premise of our study is that the set of miRNAs co-regulated by AR, HOXC6 and NKX2-2 captures the majority of miRNAs associated with metastatic prostate cancer." (PMID 28397780, 2017).
pilocytic astrocytoma (1 paper, 2022). Pilocytic astrocytoma is a rare subtype of low-grade glioma of the central nervous system characterized by a well circumscribed, often cystic, brain tumor with a discrete mural nodule and long, hair-like projections that extend from the neoplastic astrocytes. "HOXC6 expression was absent or low in normal brain tissues and pilocytic astrocytoma (PA, grade I), high in GBM, and intermediate in LGG (data not shown)." (PMID 35432534, 2022).
prostate adenocarcinoma (1 paper, 2025). "The volcano plot indicated significant upregulation of genes such as SIM2, HPN, and HOXC6 in prostate adenocarcinoma (PRAD), and significant downregulation of genes such as SLC39A2, SLC39A6, and SLC39A10." (PMID 40978029, 2025).
synovial sarcoma (1 paper, 2025). "Concomitantly, genes activated by SS18::SSX in synovial sarcoma were repressed, including HOX genes HOXC6, HOXA10 as well as SRSF1 and TYMS." (PMID 40804185, 2025).
triple-negative breast carcinoma (1 paper, 2022). An invasive breast carcinoma which is negative for expression of estrogen receptor (ER), progesterone receptor (PR), and human epidermal growth factor receptor 2 (HER2). "For miR-377-3p, studies have shown that miR-377-3p was one of the miRNA transcripts that could predict tumour progesterone status with 100% accuracy and the Linc00339/miR-377-3p/HOXC6 axis represented a novel pathway in the progression of triple-negative breast cancer." (PMID 35013577, 2022).
uterine corpus endometrial carcinoma (1 paper, 2022). A endometrial carcinoma (disease) that involves the body of uterus. "According to the TCGA and GTEx databases, HOXC6 expression was further analysed and found to be upregulated in most types of tumours but reduced in Kidney Chromophobe (KICH) and Uterine Corpus Endometrial Carcinoma (UCEC)." (PMID 35488304, 2022).